IGFBP4 (insulin like growth factor binding protein 4)
Diseases named in the same sentence as IGFBP4 in open-access papers (continued):
Sharing a sentence is not in itself a finding about the gene and the disease.
tumor (continued). "The IGFBP-4 protein was low in tumours which received IGFBP-4 gene construct which may be due to a feed back mechanism of IGFBP-4 upon its own cells." (PMID 17988381, 2007). "It indicates that the IGFBP-4 might have been used up or prior establishment of tumour could be a pre requisite for IGFBP-4 expression." (PMID 17988381, 2007). "Another possible explanation is tumour cells when deprived of IGF-I for a long time may be unable to produce IGFBP-4." (PMID 17988381, 2007). "Furthermore, the activity of Insulin like Growth Factor Binding Protein 4 (IGFBP4), which was also highly expressed in ES and ES-CSCs, is regulated by proteins of the tumour microenvironment which may include fibrillin-1." (PMID 34403115, 2021). "To analyze the potential of IGFBP-4 to monitor for disease recurrence and chemotherapeutic response, we collected serum samples from 10 patients undergoing chemotherapy following their surgical tumor removal (one stage I, one stage II, five stage III, two stage IV, and one recurrent)." (PMID 22264331, 2012). "Wild-type IGFBP4 may paradoxically increase tumour growth by serving as a reservoir of IGF1." (PMID 19536088, 2009). "IGFBP-4 levels may thus impact tumor angiogenesis and progression in colon cancer in vivo." (PMID 19025658, 2008). "Among them, upregulated genes such as CAMK2N1, IGFBP4, RGS2, WNT5A, and CDH1 have both tumor suppressor and inhibitory effects on EMT." (PMID 39768220, 2024). "Many tumor suppressors and oncogenes modulated by H2A.J play important roles in the regulation of energy metabolism (IGFBP3; IGFBP4; IGFBP5; AKR1B1; SOD2)." (PMID 39062630, 2024). "Previous studies reported that IGFBP4 can inhibit the IGF1R pathway and AKT phosphorylation to suppress tumor growth, and p-AKT protein was identified as one of the proteins regulating EMT." (PMID 37349627, 2024). "Molecules with tumor suppressor functions such as CAMK2N1, CDH1, IGFBP4, RGS2, and WNT5A were upregulated in MDA231 cells after their co-culture with DBMSCs in an IC setting." (PMID 39768220, 2024). "It is generally accepted that IGFBP1, IGFBP4, and IGFBP6 inhibit tumor development and progression, and their antitumor activity is mainly ascribable to IGF sequestering." (PMID 37686233, 2023). "For instance, In tumor-immune interface-3, pro-tumor expression markers are TIMP1, a member of MMPs involved in the degradation of the extracellular matrix, whereas IGFBP4, PFDN5, CD63 repress tumor progression." (PMID 35835774, 2022). "The results showed that the transcriptional expression levels of NDRG1 (P < 0.001), ERRFI1 (P < 0.001), IRS2 (P < 0.001), IGFBP4 (P < 0.01), and BIRC3 (P < 0.01) were significantly decreased in tumor tissues, while SOCS1 (P < 0.05) expression was increased." (PMID 35859293, 2022). "This lncRNA is related to the gene IGFBP4 which is a significant member of IGFBP family proteins; it inhibits tumor growth by inhibiting IGF-induced metabolic processes." (PMID 36072894, 2022). "The results showed that the growth factor LR interacts with PDGFB : PDGFRA, IGFBP4:FZD8, and TGFB1:SDC2 with TAMs and tumor vascular cells." (PMID 35664733, 2022). "C14 and C25 possessed FGF7, IGFBP4, and PDGFD paracrine functions, further promoting tumor growth and differentiation to the proliferative stage." (PMID 35664733, 2022). "IHC staining showed that expressions of IGFBP4, TGFBI, and SERPINA10 proteins were detected in para-tumoral normal cells and tumor cells that were mostly located in the extracellular and cytosol compartments." (PMID 34888242, 2021). "In mice, transplantation of SKOV3 cells overexpressing PAPP-A resulted in an accelerated tumor growth, most likely by promoting local IGF bioavailability through cleavage of IGF:IGFBP-4 complexes at the cell surface." (PMID 26336825, 2015). "Immunohistochemistry demonstrated the presence of IGF-IR in all but one tumor, whereas all tumors expressed PAPP-A, IGFBP-4, IGF-I and IGF-II." (PMID 26336825, 2015).
tumor (continued). "In yet another similar in vivo study, protease resistant IGFBP-4 has been shown to block IGF activity, tumour growth, and angiogenesis." (PMID 25866791, 2015). "IGFBP-4 is one of six IGFBP's, a family of regulators of normal and tumor cell biology, whose function is to inhibit IGF-I and -II binding to their receptors, IGF1R and IGF2R." (PMID 22264331, 2012). "Microvessel density in the mammary fat pad tumours transfected with pCMV (empty vector), wild-type IGFBP4 (BP4) or PAPP-A-resistant IGFBP4 (dBP4) was scored following MECA32 immunohistochemistry." (PMID 19536088, 2009). "We then investigated the expression of ESR1/ERα and that of the five following top-ranked genes (MET, FOS, SNCG, IGFBP4, and BCL2) by RTQ-PCR on the initial set of 18 tumor samples (eight control and 10 TF)." (PMID 18928543, 2008). "In our previous study, we assessed the effect of local IGFBP-4 gene therapy on a previously established subcutaneous cancer model and found that the IGFBP-4 and IGF-1R were overexpressed by the tumours." (PMID 17988381, 2007). "PLEKHS1 expression was significantly increased in G3T1 compared to G1Ta tumours (p = <0.01), whilst IGFBP2, IGFBP4, and IGF1R were significantly reduced in the more advanced tumour group (p = <0.010.03, <0.01, respectively), which were similar results to those observed in CIS." (PMID 34681810, 2021). "Given the involvement of many of these genes (such as C3, CD74, HLA-DR, STRA6, IGFBP4 and PIGR) in immune-mediated processes, it is tempting to speculate that their up-regulation indicates immune-mediated tumour control that is lost in malignant tumours." (PMID 32218455, 2020). "IGFBP4 is an important core member of the IGFBPs family, which can mediate its main functions through inhibiting IGF-induced cellular growth and thus regulate the tumor metabolic processes." (PMID 28946875, 2017). "However, some changes were observed in the levels of expression of binding protein genes, with a decrease in IGFBP2, IGFBP3, and IGFBP4 expression and an increase in IGFBP7 expression with tumor progression." (PMID 28882129, 2017). "We found that c-Src modulates migration, invasion and transendothelial migration processes by regulating the phosphorylation of focal adhesion proteins along with the levels of secreted proteins such us IGFBP4, CTGF, and Cyr61, a new exosomal protein involved in tumor progression." (PMID 25980494, 2015). "IGFBP4 may inhibit IGF-1-mediated effects, including tumor promoting ones, through the formation of IGF-1-binding complexes." (PMID 25743390, 2015). "In addition to its effects on 4T1.2 tumour cells, IGF1 stimulated growth of human dermal MVECs, an effect that was blocked by recombinant IGFBP4." (PMID 19536088, 2009). "IGFBP4 cleavage fragments were identified in 4T1.2 mammary fat pad tumour tissue but not in cultured 4T1.2 cells or conditioned medium, suggesting that PAPP-A within the tumours was produced by host cells." (PMID 19536088, 2009). "Although we saw increased endothelial cell apoptosis in tumours expressing protease-resistant IGFBP4, this was not reflected in reduced microvessel density." (PMID 19536088, 2009). "Some proteins from this list have also been identified in tumor studies as clinical outcome predictors (NOV, CLU TNC, POSTN, IGFBP2, LCN2) or mediators of resistance to chemotherapy (CLU, FBLN1, THBS, STIP1, PTGES3, IGFBP4, ATOX1)." (PMID 19936259, 2009). "In addition to ESR1/ERα, the top-ranked genes selected by statistical cross-analyses were MET, FOS, SNCG, IGFBP4, and BCL2, which were subsequently validated in a larger set of tumor samples (from 17 control patients and 18 TF patients)." (PMID 18928543, 2008). "The results showed that the IGFBP-4 gene therapy did not prevent the tumour establishment but it increased the tumour apoptosis which was associated with an increase in Bcl-2 and Bax expressions." (PMID 17988381, 2007).
tumor (continued). "In addition, proteins observed to be absent in tumor scaffolds in the LKB1 overexpressing cell line included those associated with the adipose matrix (COL6A2) and regulators of adipogenesis (IL17RB and IGFBP4), suggesting a role for LKB1 in tumor-mediated adipogenesis." (PMID 35755802, 2022). "Comparison of normal and tumor tissue at long-term culture showed increased expression of IGF1R (5-fold, p < 0.0001) and IGFBP6 (3.5-fold, p < 0.01), whereas IGFBP1 (4-fold, p < 0.05), IGFBP3 (2.5-fold, p < 0.01) and IGFBP4 (4-fold, p < 0.01) were downregulated in tumor slices." (PMID 35884847, 2022). "Indeed, ER+ tumours were scattered in subgroups 1 to 4 that are characterised by the over-expression of a cluster of genes, which includes CCND1, KRT19, IGF1R, LIV1, ESR1, GATA3, TFF1/pS2, ERBB4, PR and IGFBP4." (PMID 17338809, 2007). "Results demonstrate that tumor scaffold, in the absence of LKB1 overexpression, repressed COL1A2 and IGFBP4, and enhanced COL4A1 compared to MDA-MB-231 cells grown on TCP." (PMID 35755802, 2022). "4T1.2 cells expressed the IGF1R and IGFBP4, but not the IGFBP4 protease PAPP-A, although PAPP-A was expressed within 4T1.2 mammary fat pad tumours." (PMID 19536088, 2009).
cancer (48 papers, 1997 to 2025). A tumor composed of atypical neoplastic, often pleomorphic cells that invade other tissues. "Loss of expression of the IGFBPs, IGFBP3 and IGFBP4, has previously been linked with resistance to gefitinib in other cancer types and IGFBP-3 is frequently concomitantly overexpressed with EGFR in ESCC." (PMID 40615716, 2025). "Growing evidence suggests that loss of IGFBP4 in human cancer cells increases proliferation, migration, and invasion in vitro." (PMID 37433992, 2023). "Previous studies have shown that IGFBP4 is associated with cancers in lung, breast, liver, stomach, colon, prostate, bone, and nervous tissues." (PMID 36575438, 2022). "The IGFBP4 gene had been reported to be associated with several types of cancer, it can promote the RCC cell metastasis and activate Wnt/beta-catenin signaling pathway in humans." (PMID 32038722, 2019). "Due to its regulatory role in the IGF signaling system, IGFBP4 has emerged as a potential biomarker in various pathological conditions, such as cancer, cardiovascular diseases, and metabolic disorders." (PMID 40806552, 2025). "Since IGFBPs are strictly connected to IGFs and monitor IGF activity, the epigenetic downregulation of IGFBP-4 positively influences cancer growth by decreasing IGF inhibition." (PMID 38785834, 2024). "Conversely, IGF-independent function is connected to the IGFBP-4 control of cancer development thanks to the estrogen balance of receptor activation." (PMID 38785834, 2024). "The expression of IGFBP4/5 was decreased in almost all cancers except for KIRC, PAAD, and GBM (p < 0.05)." (PMID 37199034, 2023). "IGFBP-4, which exerts only inhibitory action on IGFs, is often overexpressed in cancer and in correlation with a state of differentiation." (PMID 36013453, 2022). "The function of IGFBP‐4 has been primarily explored in the setting of cell proliferation and angiogenesis, with a focus in cancer research." (PMID 31482149, 2019). "The involvement of the IGF pathway in cancer has led to the investigation of other components of the pathway such as IGFBP4 and PAPP-A." (PMID 30348128, 2018). "Recently, in vivo studies have showed that IGFBP-4 exerts its anti-proliferative action and inhibits the growth of some cancers." (PMID 28946875, 2017). "PAPPA can act as an autocrine or paracrine regulator of IGF action and the proposed mechanism for enhancing cancer migration is by increasing IGF release following the proteolysis of IGFBP4." (PMID 25940796, 2015). "IGFBP-4 has however been found to influence migration and invasion in cancer studies, with inhibitory or stimulatory effects on migration depending on the model examined." (PMID 25475528, 2014). "And from this list, we selected IGFBP-4 as a "proof-of-principle" candidate based on pathway analysis, proposed upregulation in other cancers as well as the availability of a commercial antibody." (PMID 22264331, 2012). "At least 50 genes in our list are already known to be regulated by DNA methylation, such as those encoding cancer antigens (a set of MAGE and GAGE), H19, S100A4, IGFBP4, UCHL1, COL1A2, CLU, FN1, and TGFBI." (PMID 19234609, 2009). "One of the IGF binding proteins called IGFBP-4 is well known for its growth inhibitory effect on several cancer cells in vitro." (PMID 17988381, 2007). "Increasing evidence illuminated that IGFBP4 plays a prominent role in different malignant tumors." (PMID 37433992, 2023). "Volcano plot showed significantly upregulated transcripts of transmembrane 4 L6 family member 1 (TM4SF1), neuritin 1 (NRN1), MT2, mucin‐like protein 3 (MUCL3), complement component 4B (C4B) and insulin‐like growth factor‐binding protein 4 (IGFBP4) genes in treated KPC mice cancer cells." (PMID 38131168, 2023). "Less IGFBP-4 is found in the cancer tissue than in the normal." (PMID 36013453, 2022).
cancer (continued). "There is vast published literature about Igfbp4 and different types of cancer." (PMID 35606887, 2022). "Mll1 also controls the intestinal stem cell genes Smoc2, Igfbp4, and Olfm4, which are induced in Wnt-mutated cancer cells but regulated by other signaling pathways such as Notch and NF-κB52,53." (PMID 33349639, 2020). "The results indicated that the expression of IGFBPs, especially IGFBP4 and IGFBP7, was significantly correlated with the suppression or activation of a variety of cancer pathways." (PMID 37088808, 2023). "Relatively speaking, IGFBP4, IGFBP7 and IGFBPL1 showed more amplifications of copy number in multiple cancer types." (PMID 37088808, 2023). "And for the majority of the cancers, IGFBP3, IGFBP4, IGFBP5, IGFBP6 and IGFBP7 were significantly positively associated with stromal, immune as well as ESTIMATE scores including COAD, PCPG, PRAD, READ and STAD." (PMID 37088808, 2023). "It has been suggested that CEFs promote the release of IGF‐I via PAPP‐A, which cleaves the complex of IGF‐I and IGFBP‐4 in vitro and activates IGF‐I receptor‐mediated signaling in cancer cells." (PMID 34379869, 2022). "Taken together, these results indicate that cancer cell-derived exosomal miR-425-3p inhibits preadipocyte proliferation and differentiation through targeting related regulating genes such as GATA2, IGFBP4, MMP15, and CEBPA." (PMID 35941833, 2022). "Thereafter, we used the PrognoScan database to investigate the prognostic value of IGFBP4 and IGFBP6 expression in patients with different types of cancer." (PMID 35832140, 2022). "The levels of both IGFBP-4 and PAPP-A are known to be elevated in various tumourderived cells and play important roles in various cancers through the IGF system." (PMID 34177367, 2021). "Accumulating evidence indicates that IGFBP-4 and PAPP-A are significantly involved in cancer development, but the evidence is insufficient." (PMID 34177367, 2021). "Upregulation of several genes, including IGFBP4, RGS2, and WNT5A, that mediate several functions, including growth, differentiation, proliferation, apoptosis, and angiogenesis, were observed in cancer cells after their treatment with DBMSCs." (PMID 39768220, 2024). "Furthermore, according to the results from CCLE analysis, IGFBP2, IGFBP3, IGFBP4 and IGFBP6 are highly expressed in most cancer cell lines at the cell level." (PMID 37088808, 2023). "Since the IGF axis could contribute to cancer progression and invasion, it is now widely accepted that aberrant methylation of IGFBP7, IGFBP-4, IGFBP-3, IGF-1R, IGF-1, and IGF-II promoters could be a potential factor in various common human cancers." (PMID 33768092, 2021). "Thus, more comprehensive assessment of the impact of lnc-IGFBP4–1 on the metabolic features of LC cells may shed new light on the molecular mechanism how lnc-RNA exerts influence to regulate metabolic programming to facilitate the cancer cell growth and metastasis." (PMID 28946875, 2017). "Here, we found that the expression of IGFBP-4 was decreased in cancer tissue and a negative correlation relationship between the expression of IGFBP4 and lnc-IGFBP4–1." (PMID 28946875, 2017). "No IGFBP-3 was secreted by any culture but 24-kDa IGFBP-4 was found in 3 out of 10 normal and 5 out of 10 cancer tissues." (PMID 9218734, 1997). "The IGFBP-4/ IGF-I/PAPP-A axis along with follistatin-like (FSTL)-3 has been shown to be surrogate markers for BC in a study involving 100 females with benign tumors, 145 females with malignant tumors (including treatment naïve and chemotherapy treated) and 100 disease-free control individuals." (PMID 38395880, 2024). "In addition, IGFBPs may play synergistic roles in various cancer-related pathways because a significant correlation was detected, such as IGFBP3-IGFBP4(r = 0.54), IGFBP4-IGFBP7(r = 0.50) and IGFBP5-IGFBP7(r = 0.49)." (PMID 37088808, 2023).
cardiovascular disease (4 papers, 2018 to 2025). "Collectively, the Stanniocalcin-2/PAPP-A/IGFBP-4 axis regulates local IGF bioavailability and signaling with potential biological implications in cardiovascular disease." (PMID 29712555, 2018).
adenocarcinoma (3 papers, 2004 to 2021). A common cancer characterized by the presence of malignant glandular cells. "Additionally, IGFBP-4 appears to be epigenetically silenced in some adenocarcinoma cells, resulting in the suppressed IGF inhibition." (PMID 34177367, 2021).
infection (3 papers, 2012 to 2023). The state of being infected such as from the introduction of a foreign agent such as serum, vaccine, antigenic substance or organism. "Meanwhile, we observed that Treg subpopulation 6 was naive Treg cells, increased after infection, and specifically expressed Gpr83 and Igfbp4." (PMID 37039643, 2023). "After infection, the Lag3hi Treg and Gpr83+Igfbp4+ naive Treg subpopulations were specifically induced in PBMCs and the spleen, respectively." (PMID 37039643, 2023). "ARDS patients with overexpressed IL-6, CXCL16, or IGFBP-4 had significantly longer hospital stay and higher incidence of secondary infection." (PMID 27095254, 2016). "Additionally, Treg cell subpopulation six was substantially increased in PBMCs and spleens of mice after infection, and its specific highly expressed genes Gpr83 and Igfbp4 have the potential to become biomarkers for the diagnosis and prognosis of CE." (PMID 37039643, 2023).
heart disease (2 papers, 2021 to 2025). "Proteins such as CDCP1, CXCL17, FGF21, GDF15, and IGFBP4 commonly mediated effects in both the Air and Noise Pollution and Social Deprivation groups, while GDF15 was notably linked to heart disease across these patterns." (PMID 41290610, 2025). "Paracrine factors, which are regarded as key regulator benefitting CDCs therapeutic effect in heart diseases, were highly expressed in iECDCs [chemokine (C-X-C motif) ligand 12 (CXCL12), VEGF, FGF, IGFBP4, etc.]." (PMID 35141286, 2021).
IGFBP4 also shares sentences with these, for which no sentence is quoted: metabolic syndrome (2 papers); metastatic tumor (2); myocardial infarction (2); Obstructive Sleep Apnea (2); osteoporosis (2); type 1 diabetes (2); viral infection (2); acute lymphoblastic leukemia (1); allergic asthma (1); amyloidosis (1); androgen excess (1); aortic stenosis (1); asthma (1); benign tumors (1); bladder cancer (1); brain cancer (1); brain injury (1); cervical cancer (1); Cognitive impairment (1); colitis (1); coronary heart disease (1); diffuse gastric adenocarcinoma (1); endothelial dysfunction (1); Familial adenomatous polyposis (1); Fanconi anemia (1); follicular adenomas (1); gastric intestinal type adenocarcinoma (1); gastrointestinal stromal tumor (1); glaucoma (1); heart failure (1).
A further 24 diseases each share a sentence with IGFBP4 in 1 paper.